SCX (scleraxis bHLH transcription factor)
Description:
Plays an early essential role in mesoderm formation, as well as a later role in formation of somite-derived chondrogenic lineages.
Synonyms: bHLHa41; bHLHa48; SCXA; SCXB
Tractability: No criterion of Open Targets' tractability assessment is met for any kind of drug.
Gene: Protein-coding gene on chromosome 8 (144,266,453 to 144,268,481, forward strand). Ensembl gene ENSG00000260428.
Subcellular location: Nucleus
Gene Ontology:
Molecular function: bHLH transcription factor binding; DNA-binding transcription activator activity, RNA polymerase II-specific; E-box binding; protein binding; DNA binding; DNA-binding transcription factor activity, RNA polymerase II-specific; RNA polymerase II transcription regulatory region sequence-specific DNA binding; sequence-specific DNA binding; DNA-binding transcription factor activity; protein dimerization activity
Biological process: positive regulation of transcription by RNA polymerase II; BMP signaling pathway; cell differentiation; chondrocyte differentiation; collagen fibril organization; deltoid tuberosity development; developmental process; DNA-templated transcription; endochondral ossification; heart valve formation; heart valve morphogenesis; mesoderm formation; negative regulation of apoptotic process; positive regulation of cartilage development; positive regulation of cell population proliferation; positive regulation of collagen biosynthetic process; positive regulation of DNA-templated transcription; positive regulation of gastrulation; positive regulation of gene expression; regulation of cartilage development; regulation of transcription by RNA polymerase II; Sertoli cell differentiation; tendon cell differentiation; tendon development; tendon formation; and 7 more
Cellular component: nucleus; transcription regulator complex; chromatin
Genetic constraint (gnomAD): Loss-of-function variants: 7 observed, 4.4 expected, observed/expected ratio (o/e) 1.59, 90% interval 0.83 to 1.94. That is too few expected variants to judge how well the gene tolerates losing a copy. Missense variants: 342 observed, 208.2 expected, observed/expected ratio (o/e) 1.64, 90% interval 1.5 to 1.8. Synonymous variants: 193 observed, 115.79 expected, observed/expected ratio (o/e) 1.67, 90% interval 1.48 to 1.87.
Homologues: Orthologues: macaque SCX (100% identical), chimpanzee SCX (99% identical), mouse Scx (96% identical), pig SCX (95% identical), guinea pig SCX (94% identical), rat Scx (90% identical), zebrafish scxa (63% identical), tropical clawed frog SCX (62% identical), zebrafish scxb (60% identical), Drosophila melanogaster CG33557 (31% identical), Drosophila melanogaster twi (20% identical), Caenorhabditis elegans hlh-8 (19% identical), and 2 more. Paralogues in human: TCF15 (52% identical), TCF21 (26% identical), MSC (25% identical), TWIST2 (25% identical), TWIST1 (24% identical), HAND1 (24% identical), BHLHA9 (23% identical), HAND2 (23% identical), PTF1A (22% identical), TCF23 (21% identical), FIGLA (20% identical), FERD3L (19% identical), and 1 more.
Diseases named in the same sentence as SCX in open-access papers:
SCX is named in the same sentence as 8 diseases in open-access papers, as found by Europe PMC text mining. Sharing a sentence is not in itself a finding about the gene and the disease. The quoted sentences say what the papers report.
tendinopathy (3 papers, 2017 to 2023). "Another finding of this study was that the SCX gene was upregulated in the tendinopathy group compared to the healthy tenocyte." (PMID 28598390, 2017). "Previous studies have shown decreased SCX expression in tendinopathy, and it is possible that lower substrate stiffness may contribute to this change." (PMID 35295642, 2022). "The results showed that tendinopathy tenocytes had higher levels of COL3A1, MMP1, COX2, SCX, ACTA2, and substance P gene expression compared to healthy tenocytes." (PMID 28598390, 2017). "As shown in the results comparing the healthy and tendinopathy samples, the relative mRNA expressions of COL3A1, COX2, SCX, MMP1, and ACTA2 were increased by 1.4, 1.8, 2.7, 1.3, and 1.6 times in the SP-treated samples compared to the PBS-controls (p < 0.05 in all), respectively." (PMID 28598390, 2017).
glioma (2 papers, 1997 to 2024). A benign or malignant brain and spinal cord tumor that arises from glial cells (astrocytes, oligodendrocytes, ependymal cells). "Intracerebrally transplanted human glioma xenografts showed an increased level of murine mdr3 gene expression, whereas scX showed only faint expression." (PMID 9275020, 1997).
diabetic nephropathies (1 paper, 2020). "In diabetic nephropathies, SCX also activates the expression of α-SMA/ACTA2 and bone morphogenetic protein 4, to promote differentiation of mesangial cells into activated myofibroblasts." (PMID 32708589, 2020).
fibrosis (1 paper, 2020). the formation of excess fibrous connective tissue in an organ or tissue in a reparative or reactive process. "Circulating SCX was also measured in patients with two diseases with different forms of fibrosis: SSc and HP." (PMID 32708589, 2020).
interstitial lung disease (1 paper, 2020). A diverse group of lung diseases that affect the lung parenchyma. "IPF patients with severely affected respiratory capacities and late-stage SSc patients presenting anti-topoisomerase I antibodies and interstitial lung disease showed the highest SCX-serum levels." (PMID 32708589, 2020).
pulmonary fibrosis (1 paper, 2020). Chronic progressive interstitial lung disorder characterized by the replacement of the lung tissue by connective tissue, leading to progressive dyspnea, respiratory failure, or right heart failure. "Serological profile results are in complete agreement with organ involvement results, where patients with pulmonary fibrosis also had high SCX serum levels in comparison to controls." (PMID 32708589, 2020). "In patients with SSc, SCX levels were increased in later stages of the disease and in patients with anti-topoisomerase I antibodies, pulmonary fibrosis (ILD-SSc), and gastrointestinal involvement." (PMID 32708589, 2020). "SCX protein expression was analyzed in the murine pulmonary fibrosis model (induced by a single intratracheal instillation of bleomycin)." (PMID 32708589, 2020). "Due to its role in regulating the expression of profibrotic genes, we expected SCX expression to be higher in primary lung fibroblasts from patients with pulmonary fibrosis." (PMID 32708589, 2020). "In a similar way to ASCL2, the original SCX function was described as relevant in embryonic development; however, its high abnormal expression in tissue characterizes pulmonary fibrosis." (PMID 32708589, 2020). "We propose that the accumulation of cells of mesenchymal origin in alveolar spaces could be responsible for high SCX expression in tissue from patients with pulmonary fibrosis." (PMID 32708589, 2020). "We observed a nonsignificant trend towards higher SCX protein levels in the lungs from mice that developed pulmonary fibrosis." (PMID 32708589, 2020). "Lungs from mice treated with subcutaneous bleomycin did not develop pulmonary fibrosis, nor increased SCX expression." (PMID 32708589, 2020).
cancer (1 paper, 2021). A tumor composed of atypical neoplastic, often pleomorphic cells that invade other tissues. "The high up-regulation of SCX in “C” was a surprise given that its expression level was not altered in the other two cancer regions." (PMID 34209090, 2021).
SCX also shares sentences with these, for which no sentence is quoted: type 2 diabetes (1 paper).